YWHAZ (tyrosine 3-monooxygenase/tryptophan 5-monooxygenase activation protein zeta)
Diseases named in the same sentence as YWHAZ in open-access papers (continued):
Sharing a sentence is not in itself a finding about the gene and the disease.
bladder cancer (9 papers, 2016 to 2022). "Aberrant expression of YWHAZ has been observed in various tumors, and it is also associated with the clinical stages of bladder cancer." (PMID 35340237, 2022). "There were 127 cases with available mutation and CNV data in the corresponding TCGA bladder cancer dataset, 20% of them had YWHAZ alteration." (PMID 27167196, 2016). "The finding implicated that YWHAZ might play protective roles in bladder cancer." (PMID 27167196, 2016). "Conversely, gene knockdown using a specific shRNA in YWHAZ‐overexpressing bladder cancer cells triggered marked increases in cell death after drug or radiation treatments." (PMID 30945298, 2019). "Because our data suggest YWHAZ exerts a suppressive effect on apoptosis in bladder cancer, we next endeavored to generate several doxorubicin‐ or cisplatin‐resistant clones from RT4 cells." (PMID 30945298, 2019). "A cell‐based functional study further confirmed that YWHAZ overexpression can drive bladder cancer toward resistance to chemo‐/radio‐therapy which can be proven by IHC staining on recurrent UCUBs after chemotherapy." (PMID 30945298, 2019). "The clinical impact of YWHAZ expression was assessed using IHC with bladder cancers at different clinical stages." (PMID 30945298, 2019). "Recent report using whole-genome sequencing techniques have identified varieties of focal copy number alterations of bladder cancer, including YWHAZ, located at 8q22, a gene involved in a wide range of biological processes." (PMID 27167196, 2016). "We explore the biological significance of YWHAZ amplification on bladder cancer, and the correlation with important other molecular events." (PMID 27167196, 2016). "In our study, we reported using the online analytical tools of The Cancer Genome Atlas (TCGA) database, to explore the biological significance of YWHAZ amplification on bladder cancer, and the correlation with important other molecular events." (PMID 27167196, 2016). "Up till now, the link between YWHAZ and biological characteristics of bladder cancer remains poorly understood." (PMID 27167196, 2016). "Further study is therefore needed to investigate the impact of YWHAZ on bladder cancer metabolism." (PMID 30945298, 2019). "Although YWHAZ has also been reported to act as a tumor suppressor during bladder cancer development 32, 33, our results consistently show that YWHAZ overexpression negatively regulates apoptosis, enabling cellular adaptation to the presence of chemotherapeutic drugs." (PMID 30945298, 2019). "TTI1, RAF1 and YWHAZ combined are found to be overexpressed in 55% of all bladder cancer cases." (PMID 30220976, 2018). "The protective role of YWHAZ in bladder cancer deserve insightful further studies." (PMID 27167196, 2016). "The amplification of YWHAZ was commonly seen in bladder cancer." (PMID 27167196, 2016). "To assess the functional role of YWHAZ in bladder cancer, we performed GSEA using the TCGA cohort to define possible pathways regulated by YWHAZ amplification/overexpression in cancer tissues." (PMID 30945298, 2019). "To further test that idea, we overexpressed YWHAZ in RT4 cells, which endogenously express lower levels of YWHAZ than do other bladder cancer cell lines." (PMID 30945298, 2019).
cervical carcinoma (8 papers, 2009 to 2022). A carcinoma arising from either the exocervical squamous epithelium or the endocervical glandular epithelium. "Finally, this miRNA has been found down-expressed in cervical cancer tissues compared with normal cervical tissues, and directly targeting the YWHAZ oncogene, hence developing its function as a tumor suppressor." (PMID 27275761, 2016). "In addition, SNHG4 can promote cervical cancer progression via regulating miR-206 and YWHAZ." (PMID 32454787, 2020).
ovarian carcinoma (7 papers, 2013 to 2023). A malignant neoplasm originating from the surface ovarian epithelium. "YWHAZ can partly eliminate the inhibitory effect caused by overexpression of miR-802 on growth and metastasis of epithelial ovarian cancer cells." (PMID 31640760, 2019). "YWHAZ also promotes ovarian cancer metastasis via vimentin‐dependent pathways and the addition of P4 decreased vimentin levels in our experiments." (PMID 32590878, 2020). "For example, it is now known that YWHAZ promotes ovarian cancer metastasis by modulating glycolysis." (PMID 32316560, 2020). "Compared with normal tissues, YWHAZ expression was obviously up regulated in epithelial ovarian cancer tissues (P < 0.01)." (PMID 31640760, 2019). "These indicated that miR-802 inhibited the progression of epithelial ovarian cancer by targeting YWHAZ." (PMID 31640760, 2019). "RT-qPCR analysis was used to measure the expression level of microRNA802 and YWHAZ in epithelial ovarian cancer." (PMID 31640760, 2019). "This study main purpose was to attest the mechanism of miRNA-802 regulation of ovarian cancer, to verify the role and relationship of YWHAZ in miRNA-802-regulated ovarian carcinoma, and to demonstrate a theoretical basis for finding new drug targets." (PMID 31640760, 2019). "miR-802 can regulate the occurrence and development of epithelial ovarian cancer by targeting YWHAZ." (PMID 31640760, 2019). "YWHAZ was obviously up-regulated in human epithelial ovarian cancer cells, and YWHAZ was negatively correlated with the expression of miR-802." (PMID 31640760, 2019). "Similarly, overexpression of YWHAZ is a prognostic biomarker for breast tumors and ovarian cancer, and a reduction in YWHAE levels has been seen in gastric carcinogenesis." (PMID 36834640, 2023). "In the process of the occurrence and development of epithelial ovarian cancer, YWHAZ signaling pathway mediated by miR-802 may play a role, but the detailed regulatory mechanism needs further study." (PMID 31640760, 2019). "Next, the expression pattern of miR-802 and YWHAZ in epithelial ovarian cancer cells was analyzed." (PMID 31640760, 2019). "MiR-802 can suppress the growth, invasion and metastasis of epithelial ovarian cancer by binding to YWHAZ, suggesting that miR-802 may be a potential tumor suppressor gene of epithelial ovarian cancer." (PMID 31640760, 2019). "We speculate that the binding of miR-802 to YWHAZ gene transcription can inhibit the translation of YWHAZ protein and regulate the biological function of epithelial ovarian cancer cells." (PMID 31640760, 2019). "In addition, YWHAZ was the binding target protein of miR-802 for epithelial ovarian cancer cells." (PMID 31640760, 2019). "The YWHAZ mechanism of action on the development of ovarian carcinoma is not clear." (PMID 31640760, 2019). "In addition, a direct negative correlation between miR-802 expression and YWHAZ levels was found in epithelial ovarian cancer tissues." (PMID 31640760, 2019).
pancreatic cancer (6 papers, 2022 to 2024). "For instance, KAT2A-mediated H3K79 succinylation in the promoter of YWHAZ (encoding 14-3-3zeta expression) is essential for β-catenin stability to promote pancreatic carcinoma metastasis." (PMID 35449131, 2022). "The biofunctions of KDELR3 and YWHAZ in pancreatic cancer (PC) cells were also investigated through colony formation, Transwell assays, flow cytometric detection and a xenograft model." (PMID 38303549, 2024). "The metastasis-promoting role of YWHAZ was further validated in human pancreatic cancer cells." (PMID 37452033, 2023). "Using this strategy, we identified YWHAZ as a key regulator of pancreatic cancer metastasis." (PMID 37452033, 2023). "Hence, our study established a high-throughput screening method to investigate the functional relevance of novel genes and validated YWHAZ as a key regulator of pancreatic cancer metastasis." (PMID 37452033, 2023). "Interestingly, our results reveal that, in contrast to KRT7, the expression of YWHAZ and GPRC5A genes demonstrates a relatively stronger correlation with B cell infiltration in pancreatic cancer." (PMID 38634049, 2024). "In contrast, YWHAZ, despite its low gene expression and not being easily detectable, is involved in tumorigenesis and progression in many tumours, including pancreatic cancer." (PMID 35711911, 2022).
bipolar disorder (5 papers, 2011 to 2024). A disorder of the brain that causes unusual shifts in mood, energy, activity levels and the ability to carry out day-to-day tasks. "Several studies have implicated 14-3-3 genes with schizophrenia and bipolar disorder, YWHAE and YWHAZ interact with disrupted in schizophrenia 1 (DISC1), and Ywhae+/– and Ywhaz–/– mice have been shown to display neurodevelopmental and schizophrenia-associated phenotypes." (PMID 27142060, 2016).
colon cancer (5 papers, 2013 to 2022). "We hypothesized that TNFRSF11B may regulate YWHAZ transcriptional activity to affect tumorigenesis in colon cancer." (PMID 34938284, 2021). "In the subset of colon cancer cell lines HSPCB, YWHAZ, and RPS13 were the 3 most stably expressed reference genes." (PMID 23554992, 2013).
diabetes (5 papers, 2014 to 2025). "Four genes (TNFRSF12A, MAP1B, EZR and YWHAZ) upregulated in donors with chronic pancreatitis were also upregulated in vimentin-positive α-cells in donors without diabetes or CF." (PMID 39836539, 2025). "Upstream regulator analysis suggested COMMD1, HIF1A, EGLN, PIK3R1 and MTORC1 as major upstream regulators for the phase shifts, while HSP90B1, YWHAZ, CNGA3, COL2A1 and TFRC were identified as the major upstream regulators for the amplitude changes observed in the diabetic retina." (PMID 38039846, 2024). "Through the PPI network screening, it was found that 5 key genes (YWHAZ, HNRNPA1, HSPA8, HSP90AA1, and HSPA5) obtained through protein interactions may provide new ideas for the treatment of diabetes." (PMID 32851081, 2020).
head and neck cancer (5 papers, 2010 to 2023). A primary or metastatic malignant neoplasm affecting the head and neck. "A critical role of 14-3-3 protein family has been described in breast, lung, and head and neck cancers, suggesting that YWHAZ plays a pro-oncogenic role in multiple tumor types." (PMID 33718136, 2021). "The knocked-down expression of 14-3-3 ζ, a gene product of YWHAZ, sensitizes head and neck cancer cells to chemotherapy." (PMID 23671674, 2013).
lung adenocarcinoma (5 papers, 2020 to 2022). A carcinoma that arises from the lung and is characterized by the presence of malignant glandular epithelial cells. "For example, Xu and Chen utilized a six AG-based pattern (APOC3, EPOR, H2AFX, MXD1, PLCG2, and YWHAZ) to structure a risk model that could efficiently stratify the existing cases in high- and low-risk groups in terms of OS in lung adenocarcinoma (LUAD)." (PMID 34976839, 2021). "The ToppFun FEA, relative to diseases, predicted a possible association of the RAC1, CFH and 5 of the 14-3-3 protein family genes, namely SFN, YWHAB, YWHAE, YWHAG and YWHAZ with lung adenocarcinoma." (PMID 35366267, 2021).
melanoma (5 papers, 2021 to 2024). A malignant, usually aggressive tumor composed of atypical, neoplastic melanocytes. "YWHAZ has been identified as a connecting factor between tyrosinase-triggered melanin production and melanoma growth, highlighting its close association with melanin synthesis." (PMID 39125816, 2024). "We found the ENSOARG00020006042 exhibited the highest similarity with the YWHAZ gene, with a comparison rate of 96%, which indicates it is potentially a member of the YWHA gene family that is associated with melanogenesis and melanoma." (PMID 39125816, 2024). "Our results display that B2M and YWHAZ represent the most optimal reference genes to reliably quantify hypoxia-inducible CYGB expression in melanoma cell lines." (PMID 34035373, 2021). "In particular, we have established that in two melanoma cell lines, Malme-3M and A375, B2M and YWHAZ are the most optimal genes to be used under experimentally-induced hypoxic conditions." (PMID 34035373, 2021). "These are EGFR, ERRFI1, IL6, JAK2, PLXNC1, RGL3 which were found to be upregulated and CBL, CDC42, PIK3R3, STAT3, UBE2D2 and YWHAZ which were found to be downregulated; Melanoma has PLXNC1 as upregulated and TGFA as downregulated gene." (PMID 34764329, 2021).
Alzheimer disease (4 papers, 2023 to 2025). A progressive, neurodegenerative disease characterized by loss of function and death of nerve cells in several areas of the brain leading to loss of cognitive function such as memory and language. "Through multi-omics SMR and single-cell validation, we identified a set of high-confidence causal genes, notably YWHAZ, which exhibits opposing dysregulation in neuronal versus glial cells in the Alzheimer’s disease brain, highlighting the cellular complexity of the pathological response." (PMID 41296471, 2025). "Multiple 14-3-3 homologues, YWHAB, YWHAE, YWHAG and YWHAZ, were also found to be consistently upregulated in Alzheimer's disease." (PMID 40491829, 2025).
COVID-19 (4 papers, 2021 to 2024). A disease caused by infection with severe acute respiratory syndrome coronavirus 2. "In the COVID-19 comparison group, five DEPs, PPP1CA, YWHAH, YWHAB, YWHAZ, and TP53BP2, were enriched with the first three upregulated and TP53BP2 downregulated, whereas the PQ group exhibited enrichment only in Smad4 within this pathway." (PMID 39301288, 2024). "In conclusion, our study provides global insights into the transcriptome profiles of host responses in COVID-19-vaccinated individuals and identifies MAPK1, CDC42, PPP2CA, EP300, YWHAZ and NRAS as hub genes that are significantly correlated with the vaccine response." (PMID 37096063, 2023).
endometriosis (4 papers, 2019 to 2026). The growth of functional endometrial tissue in anatomic sites outside the uterine body. "Together, these findings identify YWHAZ as a hormonally and transcriptionally regulated endometrial factor that is disrupted in endometriosis and tightly linked to implantation and decidual progression." (PMID 41885596, 2026). "Reduced YWHAZ expression was further validated at the protein level in both epithelial and stromal compartments of the endometrium from women with endometriosis." (PMID 41885596, 2026). "This study highlights YWHAZ as a potential molecular node connecting progesterone resistance and STAT3 dysregulation to defective endometrial function and infertility in endometriosis." (PMID 41885596, 2026).
epilepsy (4 papers, 2017 to 2024). A brain disorder characterized by episodes of abnormally increased neuronal discharge resulting in transient episodes of sensory or motor neurological dysfunction, or psychic dysfunction. "At the genetic level, the 14-3-3ζ (YWHAZ) gene is associated with human developmental delays, intellectual disability, epilepsy, dysmorphic features, amyotrophic lateral sclerosis, and heart diseases." (PMID 38674334, 2024). "The remaining group of functional proteins, including YWHAB, YWHAE, YWHAQ, and YWHAZ, that contribute to epilepsy turn out to be encoded by the so-called 14-3-3 family of proteins." (PMID 28255556, 2017). "Depletion of YWHAZ exacerbates kainic acid mediated excitatoxicty, and YWHAZ expression was decreased during epilepsy development in rat models." (PMID 30283000, 2018).
head and neck squamous cell carcinoma (4 papers, 2012 to 2022). A squamous cell carcinoma that arises from any of the following anatomic sites: lip and oral cavity, nasal cavity, paranasal sinuses, pharynx, larynx, and salivary glands. "YWHAZ has beenintroduced as candidate proto-oncogene in head and neck squamous cell carcinoma whosereduced expression causes lower level of DNA synthesis rates." (PMID 29755572, 2018). "Low level copy number gains in YWHAZ have been found in head and neck squamous cell carcinomas." (PMID 22937096, 2012).
major depression (4 papers, 2011 to 2024). "In our first WES study we identified a truncating mutation in the YWHAZ gene (c.659-660insT, p.L220Ffs*18) that was transmitted from a mother with depression to an ASD sib-pair." (PMID 32545830, 2020).
Obesity (4 papers, 2020 to 2026). Accumulation of substantial excess body fat. "Additionally, knockout of YWHAZ (14-3-3ζ) led to conspicuously lean in mouse pups and diminished visceral adipose accumulation, while overexpression of YWHAZ induced obesity-like phenotypes." (PMID 36834640, 2023). "Nonetheless, whether the corresponding proteins translated from more stably expressed genes PPIA, RPLP0, and YWHAZ are appropriate for references in protein studies of obesity, needs to be clarified in the future." (PMID 33330591, 2020). "Furthermore, to assess the overall stability of each gene during the development of obesity, the data at the four time points were included in the analysis, and the result showed that PPIA, RPLP0, and YWHAZ were more stable in expression." (PMID 33330591, 2020).
Parkinson disease (4 papers, 2014 to 2022). A progressive degenerative disorder of the central nervous system characterized by loss of dopamine producing neurons in the substantia nigra and the presence of Lewy bodies in the substantia nigra and locus coeruleus. "In amygdala, the overall piRNAs-aligned pseudogenes ratio is not different in Parkinson’s disease, but some related pseudogene-aligned piRNAs, including HSP90, MTCO1, MTCO2, YWHAZ, GAPDH, and MTND were upregulated in the PD group." (PMID 35269612, 2022).
autism (3 papers, 2016 to 2024). Persistent deficits in social interaction and communication and interaction as well as a markedly restricted repertoire of activity and interest as well as repetitive patterns of behavior. "Likewise, genes linked to ADHD (LPHN3), autism (YWHAZ), and depressive behavior (BDNF) also control neuronal fate within different brain regions." (PMID 30112632, 2019).
Cognitive impairment (3 papers, 2020 to 2024). Abnormal cognition is characterized by deficits in thinking, reasoning, or remembering. "Namely, SMOC1, ALDOA, MAP1B and YWHAZ proteins emerged as biomarker candidates with low coefficients of variation that could best discriminate AD from non-AD cases with cognitive impairment as well as predict individuals with high Tau/Aβ ratio in CSF." (PMID 32514259, 2020). "SMOC1, YWHAZ, ALDOA and MAP1B emerged as biomarker candidates that could best discriminate between individuals with AD and non-AD cognitive impairment as well as Tau/β-amyloid ratio." (PMID 32514259, 2020).
dementia (3 papers, 2022 to 2025). Loss of intellectual abilities interfering with an individual's social and occupational functions. "Our results showed that 11 of 13 (84%) proteins encoded by synaptic genes including IGF1, NRXN3, and YWHAZ were associated with an increased risk of dementia progression." (PMID 38687811, 2024). "Survival analyses from CSF proteomics from the Knight ADRC identified several synaptic genes associated with an increased risk of dementia, such as IGF1, NRXN3, and YWHAZ." (PMID 38687811, 2024). "The YWHAZ/ 14−3−3 protein, present in CSF patients, has also been shown to be involved in the rapid progression of dementia and identified as a promising therapeutic target for AD intervention." (PMID 38687811, 2024). "YWHAZ, a member of the 14‐3‐3 protein family, is involved in the regulation of brain neural development and signal transduction, while ADAM10 is associated with Aβ, the hallmark pathology of AD, which are also considered to have great application value in the clinical diagnosis of dementia." (PMID 36254251, 2022).